CASR (calcium sensing receptor)
Diseases named in the same sentence as CASR in open-access papers (continued):
Sharing a sentence is not in itself a finding about the gene and the disease.
colorectal tumors (7 papers, 2014 to 2020). "A further cause of silencing of the CaSR in colorectal tumors has been proposed to be increased expression of miR-135b and miR-146b that are considered to be oncogenic." (PMID 27679579, 2016). "In human colorectal tumors, expression of the CaSR negatively correlated with proliferation markers whereas loss of CaSR correlated with poor tumor differentiation and reduced apoptotic potential." (PMID 25701758, 2015). "We investigated whether loss of the CaSR expression in colorectal tumors is caused by DNA hypermethylation and imbalance of transcriptionally permissive/repressive histone alterations." (PMID 24691920, 2014). "This lower expression seems a consequence of epigenetic alterations since a huge number of CpG islands of the CasR gene are highly methylated in colorectal tumors." (PMID 33113952, 2020). "In colorectal tumors CaSR expression inversely correlated with expression of several proliferation markers, such as CDC6, MCM2, MCM5, MCM6, and these markers were also reduced in the colon of mice lacking the CaSR." (PMID 27803671, 2016). "The CASR P2 promoter that is GC-rich, is methylated to a greater extent in colorectal tumors relative to adjacent mucosa and this correlates with the reduced CaSR levels in the tumors." (PMID 27679579, 2016). "CaSR expression is lost in colorectal tumors, mainly due to epigenetic silencing i.e., DNA hypermethylation, histone deacetylation, increased expression of the mircroRNAs miR-135b, miR-146b." (PMID 27803671, 2016). "Our data indicate that the CaSR is a colorectal tumor suppressor gene, which can be therapeutically targeted for chemoprevention of CRC." (PMID 25701758, 2015). "We observed significantly lower CaSR mRNA expression (n = 65, p < 0.001) in colorectal tumors compared with the adjacent mucosa from the same patient." (PMID 24691920, 2014). "The expression of CaSR decreases during colorectal tumor progression and the mechanisms regulating its expression are poorly understood." (PMID 24176760, 2014). "In the present study, we investigated the role of 1,25D3, TNFα, and IL-6 on the transcriptional and translational activation of the CaSR in two cell lines representing a highly differentiated and a moderately differentiated colorectal tumor." (PMID 24176760, 2014). "Moreover, the presence of some miRNAs, such as miR-21, miR-135a, miR-135b, miR-145, miR-146b, and miR-503, reduced the expression of CasR in colorectal tumors." (PMID 33113952, 2020). "The involvement of the CaSR in mediating the anti-proliferative effects of [Ca2+]o in the colon was also described by our previous observation of a significant inverse correlation between the expression of the CaSR and the expression of replication licensing factors in colorectal tumors." (PMID 28161520, 2017). "Up-to-date there is lack of knowledge regarding the methylation status of CaSR promoter 2 in colorectal tumors." (PMID 24691920, 2014).
lung adenocarcinoma (6 papers, 2020 to 2024). A carcinoma that arises from the lung and is characterized by the presence of malignant glandular epithelial cells. "In this study, we analyzed the transcriptomic changes between lung adenocarcinoma cell lines before and after acquiring cisplatin resistance and determined that CaSR was significantly upregulated in DDP-resistant LUAD." (PMID 39113697, 2024). "In lung adenocarcinoma, CaSR was overexpressed in patients with bone metastasis, and overexpression of CaSR increased NF-κB protein levels and subsequent matrix metalloproteinases 2 and 9 to enhance tumor cell invasion." (PMID 36071984, 2022). "Western blot was used to confirm the effect of CaSR on NF-κβ protein expression in order to further analyze the mechanism of CaSR in bone metastasis of lung adenocarcinoma." (PMID 32269963, 2020). "These CaSR biological behaviors affecting tumor cells suggest that CaSR is involved in the process of lung adenocarcinoma development and bone metastasis." (PMID 32269963, 2020). "The present study provided preliminary evidence to support the mechanism of NF-κB/CaSR/PTHrP signaling pathway in tumor cells to induce OC differentiation and maturation and promote the occurrence and development of bone metastasis in lung adenocarcinoma." (PMID 32269963, 2020). "As a downstream signaling molecule of CaSR, PTHrP plays an important role in bone metastasis of lung adenocarcinoma." (PMID 32269963, 2020). "This study first analyzed 120 samples from lung adenocarcinoma patients and found that CaSR expression in lung cancer was significantly higher compared to normal lung and adjacent tissues." (PMID 32269963, 2020). "Our previous study has found that stronger bone metastatic ability in lung adenocarcinoma cells resulted in a higher CaSR expression." (PMID 32269963, 2020). "In addition, our previous study also found that stronger bone metastatic ability in the lung adenocarcinoma cell line resulted in a higher expression of CaSR." (PMID 32269963, 2020). "The underlying mechanisms may be partly due to the activation of CaSR which can promote NF-κB expression and enhance PTHrP release, thus eventually promoting the development of bone metastasis in lung adenocarcinoma." (PMID 32269963, 2020). "Moreover, lung adenocarcinoma patients with bone metastasis had higher levels of CaSR expression in lung cancer tissues compared to patients without bone metastasis." (PMID 32269963, 2020). "It was hypothesized that CaSR may be involved in bone metastasis in lung adenocarcinoma." (PMID 32269963, 2020). "Immunohistochemical analysis of 120 patients with lung adenocarcinoma demonstrated that CaSR expression was significantly increased in lung cancer tissues of lung adenocarcinoma patients with bone metastases compared to patients without." (PMID 32269963, 2020). "However, the role of CaSR in lung adenocarcinomas (LUADs) is not clear." (PMID 32671062, 2020).
renal carcinoma (6 papers, 2016 to 2024). A carcinoma arising from the epithelium of the renal parenchyma or the renal pelvis. "In renal carcinoma cells, the calcium sensing receptor (CaSR) was shown to induce proliferation, migration, and adhesion towards endothelial cells, collagen I, and fibronectin in vitro as well as the formation of bone metastases in vivo." (PMID 34064589, 2021). "Our results propose CaSR as a potent target preventing bone metastasis in renal cancer." (PMID 29644008, 2018). "Based on these intriguing findings, it was suggested that CaSR expression levels could be utilized as a novel prognostic marker for predicting renal carcinoma cell bone metastasis." (PMID 27303307, 2016). "A link has also been indicated for the CaSR in renal carcinoma metastasis." (PMID 27303307, 2016).
rheumatoid arthritis (6 papers, 2013 to 2022). A chronic, systemic autoimmune disorder characterized by inflammation in the synovial membranes and articular surfaces. "This study investigated the potential association between vascular calcification in rheumatoid arthritis (RA) and CaSR expression in circulating monocytes." (PMID 25134967, 2014). "Recently, we could show that in rheumatoid arthritis, the increased [Ca2+]ex-induced IL-1β release of monocytes is caused, in part, by increased CaSR expression." (PMID 35931812, 2022). "Monocytes in the context of rheumatoid arthritis (RA) exhibit increased CPP uptake and IL-1β release in response to CaSR signaling." (PMID 32843625, 2020).
type 2 diabetes (6 papers, 2013 to 2022). "Furthermore, the CaSR may have influenced β-cell apoptosis, which has been shown to contribute to the reduced islet mass in humans with type 2 diabetes." (PMID 28575322, 2017).
calcification (5 papers, 2014 to 2025). Process by which organic tissue becomes hardened by the physiologic deposit of calcium salts. "The present study was therefore designed to explore the potential association between vascular calcification in RA and CaSR expression in human circulating monocytes." (PMID 25134967, 2014).
DiGeorge syndrome (5 papers, 2022 to 2025). "Although 22q11.2 deletion syndrome and chromosomal abnormalities were ruled out in this case, a genetic etiology could not be ruled out as the patient was not evaluated for other genetic abnormalities such as NEBL, TBCE, FAM111A, CASR, and GNA11 mutations." (PMID 36865979, 2023).
familial isolated hyperparathyroidism (5 papers, 2009 to 2024). A rare, autosomal dominant hereditary syndrome characterized by hypercalcemia, abnormally high levels of parathyroid hormone, and isolated hyperfunctioning parathyroid tumors. "Familial isolated hyperparathyroidism (FIHP) may be due to incomplete penetrance of mutations causing syndromic PHPTs, as the genes found in FIHP overlap, for example, MEN1, CDC73, or CASR." (PMID 38038882, 2024).
inflammatory bowel disease (5 papers, 2019 to 2025). A spectrum of small and large bowel inflammatory diseases of unknown etiology. "Background/Objectives: The extracellular calcium-sensing receptor (CaSR) is a multifunctional receptor proposed as a possible drug target for inflammatory bowel disease." (PMID 39770982, 2024). "Conversely, previous studies suggested a protective role for the CaSR in intestinal inflammation, which highlights the CaSR as a promising target for inflammatory bowel disease (IBD) treatment." (PMID 31888253, 2019). "Since calcilytics inhibit ligand-mediated CaSR signaling, they may be considered for novel therapies against inflammatory bowel disease." (PMID 37153788, 2023). "Phenome-wide association study data suggested that modulating DGKD, CASR, CYP24A1, or SLC34A1 may result in target-mediated adverse effects including alterations in serum bilirubin, inflammatory bowel disease, migraine, atopic dermatitis, and eczematous phenotypes." (PMID 40372791, 2025). "While dietary modulation of the CaSR had no beneficial effects, pharmacological inhibition of the CaSR may have the potential of a novel add-on therapy in the treatment of inflammatory bowel diseases." (PMID 31888253, 2019).
lung carcinoma (5 papers, 2020 to 2024). "Nevertheless, little is known about the role of CaSR in lung cancer and its contribution to chemoresistance in lung cancer." (PMID 39113697, 2024). "In lung cancer, CaSR is also highly expressed in LUAD tissues, and the expression level thereof is associated with the degrees of cancer differentiation and metastasis." (PMID 39113697, 2024). "CaSR has also been reported as a potential biomarker for predicting bone metastasis and prognosis in lung cancer patients." (PMID 39113697, 2024). "Another study found that the increase of CASR was the result of PTHrP and NF-κB upregulation, which was also positively correlated with bone metastasis in lung cancer." (PMID 34722241, 2021). "This evidence attracted attention to CASR as a new biomarker for the prediction of lung cancer bone metastasis." (PMID 34722241, 2021). "Previous studies have found that CaSR expression is the strongest in lung cancer A549 cells with the highest bone metastasis ability." (PMID 32269963, 2020). "CaSR expression in bone metastasis patients was significantly higher than that in primary lung cancer tissues (p < 0.01)." (PMID 32269963, 2020). "The present study first confirmed CaSR expression in lung cancer, lung cancer bone metastasis, and bone metastasis tissues." (PMID 32269963, 2020). "So far, three published studies reported the function of CaSR in lung cancers." (PMID 32671062, 2020). "Therefore, we examined the impact of CASR inhibitors on cisplatin resistance in lung cancer." (PMID 39113697, 2024). "The expression of CaSR in lung cancer tissues with bone metastasis was higher than that in non-metastatic lung cancer tissues." (PMID 32269963, 2020).
metastatic tumor (5 papers, 2013 to 2026). "In keeping with our previous data, this allegedly less active form of the CaSR was associated with the histological subgroup of undifferentiated neuroblastomas, metastatic disease and inferior OS rates." (PMID 23533647, 2013). "This study aimed to i/ develop a model allowing an in vivo demonstration of the involvement of the CaSR on metastatic tumor osteolytic potential and to ii/ investigate if CaSR activity could influence osteolysis though a mechanism different from PTHrP modulation." (PMID 28915604, 2017). "Elevated expression of the CaSR in aggressive metastatic tumors has been suggested as a potential novel prognostic marker for predicting metastasis, especially to bone tissue where extracellular calcium concentrations may be sufficiently high to activate the receptor." (PMID 27303307, 2016).
Myocardial fibrosis (5 papers, 2020 to 2025). "indicates that moderate activation of CaSR can exert protective effects, including maintaining myocardial contractility and alleviating myocardial fibrosis." (PMID 41208959, 2025). "CASR not only significantly improved the degree of myocardial fibrosis, inflammatory infiltration, and blood viscosity but also reduced the levels of IL-6, ET, TC, and LDL-C and increased the level of HDL-C." (PMID 36016561, 2022). "The role of Calhex231, a specific inhibitor of CaSR, in myocardial fibrosis following MI is still unclear." (PMID 33043596, 2020). "Our results suggested that after MI, CaSR was activated and up‐regulated, and the cardiac function, autophagy, inflammatory cell infiltration, inflammatory cytokine secretion and myocardial fibrosis of rats were aggravated." (PMID 33043596, 2020). "Previous studies suggested that the inhibition of the CaSR by Calhex231 could alleviate high-glucose-induced myocardial fibrosis via inhibiting the ubiquitin–proteasome pathway." (PMID 36231037, 2022). "However, the mechanism of the opposite effects of high glucose on the expression of the CaSR in cardiomyocytes and cardiac fibroblasts is still unclear, which may promote cell differentiation and contribute to myocardial fibrosis in DCM." (PMID 36231037, 2022). "In primary neonatal rat cardiac fibroblasts, high glucose induced myocardial fibrosis via the upregulation of the TGF-β1/Smads pathway, which was promoted by the CaSR agonist R568 but reduced by the CaSR inhibitor Calhex231." (PMID 36231037, 2022). "Following this study, R568 increased CaSR content in SHR myocardial tissue, lowered blood pressure, promoted macrophages to M2Mφs and improved myocardial fibrosis, but interestingly, both M1Mφs and M2Mφs were increased in the peritoneal cavity of SHRs, the number of M2Mφs remained lower than M1Mφs." (PMID 38715976, 2024). "CaSR upregulation in CFs may lead to an increase in intracellular Ca2+, and further activate the TGF-β1/SMADs pathway, promoting the proliferation and activation of fibroblasts, ultimately resulting in myocardial fibrosis." (PMID 41208959, 2025). "In this study, MI rats and peritoneal macrophages were treated with Calhex231, CaSR agonist, autophagy agonist, and antagonist or the inhibitor of NLRP3 inflammasome in order to elucidate the role and molecular mechanism of Calhex231 in myocardial fibrosis post MI." (PMID 33043596, 2020).
osteosarcoma (5 papers, 2021 to 2026). A usually aggressive malignant bone-forming mesenchymal neoplasm, predominantly affecting adolescents and young adults. "This study examined the effect of calcium-sensing receptor (CaSR) antagonism on human osteosarcoma cells and investigated the underlying molecular mechanisms of this effect through transcriptome sequencing." (PMID 41522513, 2026). "This study was designed as an exploratory investigation to evaluate the effects of CaSR antagonism on human osteosarcoma cells and to uncover associated molecular mechanisms using transcriptomic analysis." (PMID 41522513, 2026). "We found that a CaSR antagonist promoted the expression of genes associated with cholesterol and steroid synthesis in osteosarcoma cells." (PMID 41522513, 2026). "Human osteosarcoma cell lines MG-63 and Saos-2 were treated with different concentrations (0.1–10 μM) of the CaSR antagonist NPS-2143." (PMID 41522513, 2026). "Previous studies have shown that CaSR expression is upregulated in osteosarcoma cells, suggesting its involvement in tumor proliferation and invasiveness." (PMID 41522513, 2026). "Although further validation is warranted, our results provide preliminary evidence implicating cholesterol biosynthesis as a mechanistic target in osteosarcoma and underscore the exploratory value of CaSR antagonists as metabolic regulators in cancer research." (PMID 41522513, 2026). "Rather than assessing therapeutic selectivity or safety, our aim was to gain mechanistic insights into CaSR-regulated pathways and to identify potential targets for future therapeutic development in osteosarcoma." (PMID 41522513, 2026). "In this study, the MG-63 and Saos-2 cell lines were selected to validate the effects of CaSR antagonism on osteosarcoma cells." (PMID 41522513, 2026). "This study demonstrates that CaSR antagonism reduces the viability of human osteosarcoma cells in vitro." (PMID 41522513, 2026). "We analyzed the transcriptomic effects of CaSR antagonism on osteosarcoma cells to identify pathways potentially involved in reduced cell viability." (PMID 41522513, 2026). "Although these studies established a connection between CaSR activity and osteosarcoma cell behavior, the functional consequences of CaSR modulation and the underlying molecular mechanisms remain poorly understood." (PMID 41522513, 2026). "Further studies involving animal models and patient-derived samples are warranted to verify the mechanistic insights and assess the therapeutic potential of CaSR antagonists in osteosarcoma." (PMID 41522513, 2026). "In preliminary analyses we also found that a correlation existed between the native protein levels of CaSR and Homer1 in the commonly used osteosarcoma cell lines MG63 (ATCC® CRL-1427TM) and SAOS-2 (ATCC® HTB-85TM)." (PMID 34204449, 2021). "Our results were similar to a study that showed that CAV1 inhibited osteosarcoma cell (Saos-2 cell line) proliferation and invasion by upregulating the calcium sensing-receptor CaSR." (PMID 33886809, 2021). "CaSR is aberrantly expressed in osteosarcoma cells and may regulate tumor growth and invasiveness through intracellular calcium signaling pathways." (PMID 41522513, 2026). "Therefore, we suggest that CaSR antagonists have potential for use in the treatment of osteosarcoma." (PMID 41522513, 2026). "Our results confirm that CaSR antagonism inhibits the viability of osteosarcoma cells in vitro." (PMID 41522513, 2026). "While CaSR exhibits divergent roles across cancer types, it has been shown to be upregulated in MG-63 osteosarcoma cells compared to normal osteoblasts in vitro, where it may modulate proliferation, apoptosis, and invasion via calcium signaling." (PMID 41522513, 2026). "Investigating their transcriptomic effects in osteosarcoma may therefore provide new insights into CaSR-mediated regulatory networks and enhance our understanding of the molecular mechanisms driving tumor progression." (PMID 41522513, 2026).
osteosarcoma (continued). "In MG63 osteosarcoma cells, CaSR and HOMER1 co-regulate AKT Ser473 and GSK3β-S9 phosphorylation." (PMID 40059879, 2025). "The involvement of CaSR and Homer1 in AKT Ser 473 and GSK 3β-S9 phosphorylation has been demonstrated in MG 63 osteosarcoma cells." (PMID 40059879, 2025). "Whether increased CaSR/Homer1 expression and resultant AKT activation contributes to the high survival, high growth phenotype of osteosarcoma cells and are thus potential targets for the chemotherapy of osteosarcoma, remains to be determined." (PMID 34204449, 2021). "Both osteosarcoma cell lines exhibited markedly enhanced Homer1 expression compared to primary osteoblasts, along with increased expression of CaSR, mTOR, the mTORC2 specific protein Rictor, but not the mTORC1 specific Raptor, and the effects were particularly pronounced in SAOS-2." (PMID 34204449, 2021).